SYNDIG1 (synapse differentiation inducing 1)
Description:
May regulate AMPA receptor content at nascent synapses, and have a role in postsynaptic development and maturation.
Synonyms: DSPC2; C20orf39; TMEM90B; FLJ14220; IFITMD5
Tractability: Antibody: UniProt places it where antibodies can reach, with medium confidence; UniProt predicts a signal peptide or a membrane-spanning region; its Gene Ontology location is reachable by antibodies, with medium confidence.
Gene: Protein-coding gene on chromosome 20 (24,468,025 to 24,666,616, forward strand). Ensembl gene ENSG00000101463.
Subcellular location: Cell membrane; Early endosome membrane; Postsynaptic density membrane; Synapse; Cell projection, dendrite; Cell projection, dendritic spine
Subcellular location (Human Protein Atlas): Vesicles
Gene Ontology:
Molecular function: protein binding; glutamate receptor binding; protein homodimerization activity
Biological process: positive regulation of synapse assembly; intracellular protein transport; synaptic vesicle clustering; regulation of postsynapse assembly
Cellular component: cell body; dendritic shaft; dendritic spine; early endosome membrane; excitatory synapse; plasma membrane; postsynaptic density; postsynaptic density membrane; synaptic vesicle membrane; dendrite; glutamatergic synapse; membrane; synapse
Genetic constraint (gnomAD): Loss-of-function variants: 4 observed, 7.34 expected, observed/expected ratio (o/e) 0.54, 90% interval 0.27 to 1.24. That is too few expected variants to judge how well the gene tolerates losing a copy. Missense variants: 121 observed, 138.24 expected, observed/expected ratio (o/e) 0.88, 90% interval 0.75 to 1.02. Synonymous variants: 55 observed, 60.1 expected, observed/expected ratio (o/e) 0.92, 90% interval 0.74 to 1.15.
Homologues: Orthologues: chimpanzee SYNDIG1 (100% identical), macaque SYNDIG1 (94% identical), dog SYNDIG1 (94% identical), mouse Syndig1 (93% identical), rat Syndig1 (91% identical), pig SYNDIG1 (90% identical), guinea pig SYNDIG1 (85% identical), tropical clawed frog syndig1 (83% identical), rabbit SYNDIG1 (77% identical), zebrafish SYNDIG1 (67% identical). Paralogues in human: SYNDIG1L (41% identical), TMEM91 (26% identical), PMIS2 (13% identical).
Diseases named in the same sentence as SYNDIG1 in open-access papers:
SYNDIG1 is named in the same sentence as 11 diseases in open-access papers, as found by Europe PMC text mining. Sharing a sentence is not in itself a finding about the gene and the disease. The quoted sentences say what the papers report.
breast carcinoma (3 papers, 2020 to 2024). "SYNDIG1 is a prognostic immune factor in diffuse large B-cell lymphoma and breast cancer." (PMID 36591507, 2022). "In addition, a large number of additional detected genes did not fit into known breast cancer progression mechanisms (e.g. SYNDIG1, OVCH2, OR5P3, etc.)and further studies of these targets may yield new insights into additional mechanisms that support breast cancer progression." (PMID 38523186, 2024).
diabetes (2 papers, 2022 to 2024). "Other genes encode proteins involved in calcium handling (BMP3 and SYNDIG1) or are associated with diabetes mellitus (GLIS3 and TRIB3), suggesting a potential link to accelerated atherosclerosis development." (PMID 38725839, 2024).
Huntington disease (2 papers, 2013 to 2020). Huntington disease (HD) is a rare neurodegenerative disorder of the central nervous system characterized by unwanted choreatic movements, behavioral and psychiatric disturbances and dementia. "Virtually nothing is known about the two vertebrate paralogues of SynDIG1, SynDIG1L and TMEM91, although SynDIG1L has been found downregulated in mouse models of Huntington's disease." (PMID 33108974, 2020).
thyroid cancer (2 papers, 2022 to 2025). "For example, SynDIG1 has been found to be associated with depressive symptoms and can be used as a biomolecule to predict thyroid cancer." (PMID 40211847, 2025). "First, we verified the expression of 9 immune-related prognostic factors, AKAP12, APOC1, TIMP3, ADAMTS9, ANK2, HTRA3, SYNDIG1, ​​ADAMTS5 and DACT1, in 11 thyroid cancer cell lines in the CCLE database." (PMID 36591507, 2022).
Anxiety (1 paper, 2020). Intense feelings of nervousness, tension, or panic often arise in response to interpersonal stresses. "We performed correlation analysis, to explore the association of DLG2 and SynDIG1 expression with anxiety- and depression-like behavior in mice." (PMID 32290523, 2020). "In this study, we aimed to investigate the effect of ATRA on the expression of two synaptic- associated genes, DLG2 and SynDIG1, in the hippocampus and their relationship with anxiety- or depression-like behavior in young mice." (PMID 32290523, 2020).
depression (1 paper, 2020). "Whether increased expression of SynDIG1 might be associated with excitatory synaptic glutamatergic transmission in the hippocampus, which was paralleled by depression-like behavior induced by ATRA administration, needs further study." (PMID 32290523, 2020). "The strong correlation after ATRA exposure suggests that changes in SynDIG1 mRNA levels were paralleled by and strongly linked to depressive symptoms; however, the specific role of SynDIG1 in the pathogenesis of depression has yet to be determined." (PMID 32290523, 2020).
Cardiovascular disease (1 paper, 2024). "Among these, 10 regions, proximal to or within the genes OVAAL, BMP3, RIOK1, AC096553.5, MCPH1, KCNU1, GLIS3, TUT7, TRIB3, and SYNDIG1, represent novel associations with MI and have not been previously linked to Cardiovascular disease (CVD)-related traits." (PMID 38725839, 2024).
SYNDIG1 also shares sentences with these, for which no sentence is quoted: atherosclerosis (1 paper); cancer (1); diffuse large B-cell lymphoma (1); schizophrenia (1).